TUBB4B (tubulin beta 4B class IVb)
Diseases named in the same sentence as TUBB4B in open-access papers (continued):
Sharing a sentence is not in itself a finding about the gene and the disease.
cancer (17 papers, 2016 to 2025). A tumor composed of atypical neoplastic, often pleomorphic cells that invade other tissues. "Tubulin heterogeneity, which includes TUBB4B, has also been linked to the development of drug resistance in cancer." (PMID 38891892, 2024). "A recent study has implicated TUBB4B as an essential factor required for the maintenance of cancer stem cell niche via its interaction with Ephrin-B1." (PMID 37784035, 2023). "The regulatory effects of changes in TUBB3 and TUBB4B levels on cancer progression have been studied." (PMID 35741845, 2022). "Changes of TUBB3 and TUBB4B levels have been studied with respect to the regulation of cancer progression." (PMID 31375012, 2019). "By analysing the regulation of TUBB3 and TUBB4B levels in the development of non-small cell lung cancer and prostate cancer, we understand the characteristic mechanism of cancer cells’ reduced sensitivity to vinca alkaloids and taxanes, and other tubulin-binding agents (TBA)." (PMID 35741845, 2022). "TUBB4B was not seen at all associated to any of the hallmarks of cancer, which could be due to the lack of hallmark association studies of this gene." (PMID 37784035, 2023). "Lrp1 may modulates cancer progression, and Tubb4b may be related to human cancer." (PMID 32256870, 2020). "Genes related to cancer stem cells and tumorigenesis, such as KPNA2, ECT2, ERCC6L and TUBB4B, and the cell-cycle regulators DLGAP5, KIF2C and BUB3 were also significantly upregulated in the CSPG+ group, and clustered well within the same area." (PMID 38251863, 2024). "Changes in tubulin-β4 (TUBB4B) and acylglycerophosphate acyltransferase (AGPAT) expressions have been reported with respect to tumor progression and clinic outcomes of cancer patients." (PMID 34852326, 2021). "It is worthwhile to mention here that, like TUBB4B, its close relatives TUBB2 and TUBB3 have been shown to predict poor survival, the former regulating the cancer energetics through VDAC and the latter by imparting resistance to microtubule targeting agents." (PMID 35004310, 2021). "Thus far, we have shown clear evidence of the involvement of TUBB4B in the maintenance of CSC and the presence in CSC niche using in vitro, in vivo tumor models and cancer tissue sections." (PMID 35004310, 2021). "Understanding of the well-characterized mechanism of decreased sensitivity of cancer cells to tubulin-binding agents (TBAs) like vinca alkaloids and taxanes, comes from the analysis of TUBB3 and TUBB4B level regulation in non-small cell lung cancer and prostate cancer development." (PMID 31375012, 2019).
tumor (8 papers, 2018 to 2025). "Consistent with that, the tumor initiation potential in vitro and in vivo of TUBB4B knocked-down cells was significantly low." (PMID 35004310, 2021). "It is important to note that modulations of the expression of tubulins, including TUBB4B, occur during tumor progression and contribute to cell survival and induction of chemoresistance." (PMID 31375012, 2019). "Furthermore, μ-21 could potentially inhibit tumor cell proliferation and reduce the immunosuppressiveness of the tumor microenvironment via regulation of microtubule component TUBB4B and the matrix protein LAMB1, respectively." (PMID 41373892, 2025). "Here, we show that the knockdown of TUBB4B downregulates the expression of pluripotency markers, depletes ALDH1A1+ population, decreases in vitro sphere formation, and diminishes the tumor initiation potential in vivo." (PMID 35004310, 2021). "NEK2 was altered in 22.9% of analyzed tumor samples and found interacted with the α-tubulin isoforms TUBA1A, TUBA4A, the β-tubulin isoforms TUBB, TUBB4A, TUBB4B and all the γ-tubulin isoforms." (PMID 30126203, 2018). "We found that taxane-resistant tumor showed elevated expression levels of TUBB1 and lower expression levels of TUBB3, TUBB4B, and TUBB6 genes when compared with the sensitive tumors." (PMID 30126203, 2018). "On day 40, there was a significant reduction in the tumor burden, evidenced by the total flux, in the TUBB4B depleted 105 group, which was not evident in the 106 groups." (PMID 35004310, 2021). "Statistical significance of tumor-initiating potential in the two groups was analyzed by ELDA, which computed the stem cell frequency in the uninduced group as 1:25,978, in contrast to 1:3,17,756 in the TUBB4B downregulated group with a p-value of 0.00422." (PMID 35004310, 2021).
infection (3 papers, 2019 to 2025). The state of being infected such as from the introduction of a foreign agent such as serum, vaccine, antigenic substance or organism. "The analysis also identified four tubulin genes (Tubb2A, Tubb2b, Tubb3 and Tubb4B) which have previously been associated with E. coli pathogenesis, to be up-regulated in the asymptomatic (resilient to infection) dataset." (PMID 30709726, 2019). "Further validation confirmed that knockdown of these candidates significantly reduced OVM internalization, which consequently led to a substantial decrease in OVM infection, with knockdown of TUBB4B exhibiting the most potent effect." (PMID 41053536, 2025).
neurological disorders (2 papers, 2020 to 2024). "Mutations in TUBB4B have been linked to various neurological disorders that affect nervous system development and function." (PMID 38965236, 2024).
renal disease (1 paper, 2024). "In contrast, the syndromic PCD+SND variant (p.P358S) could robustly integrate into axonemes and acted in a dominant-negative manner to disrupt the microtubule lattice, thereby leading to additional sensory and renal disease phenotypes in any tissues where TUBB4B was highly expressed." (PMID 38662826, 2024).
TUBB4B also shares sentences with these, for which no sentence is quoted: hyperopia (2 papers); hypophosphatemic rickets (2); Acute myeloid leukaemia (1); asthenospermia (1); atherosclerosis (1); auditory neuropathy spectrum disorder (1); breast carcinoma (1); deafness (1); dementia (1); ischemic stroke (1); Jaundice (1); leukaemia (1); lymphedema (1); male infertility (1); microcephaly (1); prion disease (1); prostate carcinoma (1); Refsum disease (1); renal Fanconi Syndrome (1); retinal (1); retinal disease (1); sensorineural hearing loss (1); skin toxicity (1); Stickler syndrome (1); Stroke (1); varicocele (1).